NOTCH1 (notch receptor 1)
Diseases named in the same sentence as NOTCH1 in open-access papers (continued):
Sharing a sentence is not in itself a finding about the gene and the disease.
melanoma (continued). "In addition, activated Notch1 increases the stability of β-catenin that play important role in melanoma cell migration and proliferation." (PMID 28137308, 2017). "Our data demonstrated that turning ‘ON’ Notch1 signaling in MSC-DF could inhibit melanoma invasion and metastasis." (PMID 27813493, 2016). "It is a captivating observation that Notch1 activation or inactivation in MSC-DF can significantly yet oppositely regulate melanoma spheroid formation, a characteristic of cancer stem cells in which tumor-initiating cells and metastasis-initiating cells reside." (PMID 27813493, 2016). "Grafting B16-F10 cells onto skin of GOFNotch1 and LOFNotch1 mice offer unique syngeneic murine melanoma models for deciphering role of Notch1 signaling in governing tumor-regulating function of CAF in TME in which the entire cellular components of tumor stroma are composed of natural host cells." (PMID 26562315, 2015). "SKMEL28, uniquely in our panel, contains a mutation in NOTCH1, a transmembrane protein that has been shown to interact with membrane bound ligands and it can also activate MAPK signaling and PI3K signaling in melanoma." (PMID 26405815, 2015). "The initiation process of cellular invasion in melanoma might be a common feature in all melanomas via up-regulation of early embryonic genes such as Notch1 and nodal, or via up-regulation of neural crest signaling." (PMID 23342051, 2013). "Investigation of the expression of Notch receptors and their ligands in benign and malignant cutaneous melanocytic lesions indicate that Notch1 and Notch2, as well as their ligands are significantly upregulated in atypical nevi and melanomas, compared to common melanocytic nevi." (PMID 19828018, 2009). "In conclusion, although the precise details of the mechanisms by which Notch1 signaling can contribute to melanoma development remain to be defined, Notch1 could be clearly considered as a novel candidate gene implicated in melanomagenesis." (PMID 19828018, 2009). "However, Notch1 signaling is reactivated in several cancers including melanoma." (PMID 39491031, 2024). "In this study, we investigated the role of Notch signaling in melanoma tumor development and growth using the genetic model of mouse melanoma by crossing BRAFCA/+/Pten+/+/Tyr-CreER+ (B) and BRAFCA/+/Pten-/-/Tyr-CreER + (BP) mice with Notch1 or Notch2 floxed allele mice." (PMID 36672468, 2023). "Hence, the research group used a Notch-1 inhibitor to restore sensitivity, indicating that Notch-1 knockdown could be a therapeutic strategy in melanomas and drug-resistant breast malignancies." (PMID 37397377, 2023). "Importantly, Notch1 activation enabled primary melanoma cells to acquire metastatic capabilities." (PMID 32028262, 2020). "Furthermore, another study demonstrated that the Notch1-WISP-1 axis governs stromal regulation of melanoma metastasis, indicating that this axis could be a potential target for the treatment of melanoma metastasis." (PMID 30651114, 2019). "To explore whether regulation of tumor growth by Notch1 expression in melanoma cells was due to host immune status, we subcutaneously inoculated B16- shCon, B16-shNotch1, or B16-Notch1 melanoma cells into BALB/c Nude mice, which are deficient in T, B and NK cells." (PMID 29301578, 2018). "Notch1 inhibition could potently prevent inactive FBXW7‐induced melanoma tumorigenesis, rendering Notch signaling as a promising therapeutic target in the subset of melanoma patients harboring FBXW7 mutations." (PMID 28544818, 2017). "In addition, recent data showed that Andrographolide may act as a potent anti-cancer agent by targeting Notch1 pathway in CSCs that ultimately suppresses malignant melanoma growth." (PMID 28137308, 2017).
melanoma (continued). "In contrast, CM of MSC-DFNotch1−/− considerably increased the migration of melanoma cells when compared to CM of MSC-DFNotch1+/+ (bottom); thus, suggesting that Notch1 signaling may regulate MSC-DF to release soluble factor(s) that modulates the migration of melanoma cells." (PMID 27813493, 2016). "Hence, Notch1 target gene(s) identified by this approach may serve as a potential therapeutic target for melanoma metastasis." (PMID 27813493, 2016). "Similarly, in melanoma development, Notch1 is transcriptionally regulated." (PMID 22363487, 2012). "On the other hand, a tumor suppressor role for Notch1 and Notch2 was reported in a BRAFV600E/Ptennull transgenic model of mouse melanoma." (PMID 40574005, 2025). "For P1, clusters enriched in ER lumen-associated proteins (CIP2A, OSMR, WWTR1), inflammasome-related proteins, and melanoma-specific proteins (CCND1, MITF, MLANA, NOTCH1) were notable." (PMID 40669378, 2025). "Lastly, TCGA dataset revealed that TIPE has a positive relationship with CSCs markers including BMI1, NANOG, NOTCH1, and POU5F1 in melanoma." (PMID 39728923, 2024). "TCGA dataset revealed that TIPE has a positive relationship with CSCs markers, including BMI1, NANOG, NOTCH1, and POU5F1 in melanoma." (PMID 39728923, 2024). "Thus, anti-Notch1 could represent a novel addition to the immunotherapy repertoire for melanoma." (PMID 39491031, 2024). "Mechanistically, we find inhibition of Notch1 increases CD8+ T cell degranulation and IFNγ and Granzyme B production both in vitro and in vivo, leading to melanoma cell killing." (PMID 39491031, 2024). "Specifically, some Notch signaling molecules (e.g., Notch1, Notch2, Hes1) were expressed higher in M1-TAMs than in M2-TAMs in a B16F10 melanoma in vivo model." (PMID 37131214, 2023). "It was observed that when Notch-1 is activated, BRAF (V600E) melanoma cells develop acquired resistance to MAPK inhibitors and breast cancer cells also exhibit resistance to tamoxifen." (PMID 37397377, 2023). "In one such study, the constitutive expression NICD1, the activated form of Notch1, was shown to induce the aggressive growth of vertical growth phase (VGP) primary melanoma cell lines in vivo with metastatic activity." (PMID 36672468, 2023). "Previous studies have shown that Notch1 represses the infiltration of CD8(+) cytotoxic T lymphocytes and NK cells and inhibits the release of IFN-γ in melanoma." (PMID 36119057, 2022). "It was reported that, similarly to DLK1, DLK2 affects the growth of SK-MEL-2 melanoma cells, and the nature of its effects depends upon DLK2 expression levels and the degree of inhibition of NOTCH1 activation." (PMID 35163478, 2022). "Activation of Notch1 signaling has been found to enhance MAPK activity via Notch1/MAML cascade-mediated transcription, and then induced melanoma cell growth." (PMID 35016680, 2022). "A review mentioned that Notch and ERBB signaling components (i.e., Notch1, Hey1, and ERBB3) are re-expressed in melanoma in a correlative manner, and proposed that the tumorigenesis and development of melanoma require two cascade functions." (PMID 34729100, 2021). "In this study, we observed dysregulation of G9a in melanoma samples, repression of Notch1 and Hes1 expression via G9a inhibitor UNC0642, and inhibition of melanoma cell growth." (PMID 32015216, 2020). "Together, CD133/Notch1 regulate proteins such as MMPs and VEGF, thus regulating melanoma progression, angiogenesis and metastasis." (PMID 32796631, 2020). "In melanoma cells, hyperactivated PI3K/Akt signaling led to upregulation of Notch1 through NF-kappa B activity." (PMID 32015216, 2020). "Here, we created MSC-DF and utilized gain-of-function (GOF) and loss-of-function (LOF) approaches to comprehensively decipher the roles of Notch1 signaling and its downstream mediator, WISP-1, in determining the melanoma-regulating function of MSC-DF." (PMID 27813493, 2016).
melanoma (continued). "For example, in a fraction of human melanoma tumors with acquired resistance to RAF or RAF+MEK inhibition, we found evidence of Notch1 activation through elevated expression of the protein and its transcriptional targets." (PMID 27738492, 2016). "The interdependency of Notch1 and ATR/ChK1 pathways and the sensitivity of melanoma cells to their concurrent inhibition, is comparable to the synthetic lethal interactions observed for example in BRCA mutated tumor cells and PARP (poly (ADP-ribose) polymerase) inhibitors (PARPi)." (PMID 40437523, 2025). "Notch1, for example, is highly expressed in ~60% of melanomas and nearly absent in normal melanocytes." (PMID 40806546, 2025). "Indeed, we recently demonstrated that selective targeting of Notch1 via a novel neutralizing monoclonal antibody (anti-N1), significantly enchased the efficacy of anti-PD1 in melanoma syngeneic models." (PMID 40437523, 2025). "In our study, HH044 downregulated WNT5A, a contributor to Hedgehog signaling and a known druggable target for melanoma, and nNOS inhibition did not have a direct effect on Notch1 or Notch2 expression alone." (PMID 40574005, 2025). "Overall, these data support a critical role of Notch1 signaling in melanoma response to ICI and may potentially represent a predictor of ICI response in melanoma patients." (PMID 39491031, 2024). "We have previously shown that Notch1 expressing melanomas are characterized by an immune-suppressed, non-inflamed tumor microenvironment enriched in Tregs, MDSCs and immunosuppressive cytokines." (PMID 39491031, 2024). "We and others have shown that over 60% of melanomas, irrespective of driver mutation status (BRAF, RAS) express active Notch1, and that Notch1 is associated with poorer outcome and progression." (PMID 39491031, 2024). "We have previously shown Notch1 contributes to a non-inflamed TME in melanoma that reduces the response to ICI." (PMID 39491031, 2024). "In addition, Demcizumab (anti-Notch ligand, DLL4 antibody), OMP-52M51 (anti-Notch1 antibody), and OMP-18R5 (anti-Wnt receptor, FZD monoclonal antibody) are expected to be better therapeutic agents in the future against melanoma." (PMID 39611156, 2024). "Mechanistically, the effect of activated NOTCH1 in fibroblasts to suppress melanoma growth and angiogenesis has been shown to be mediated by the secretion of wnt-induced secreted protein-1 (WSP-1) and identifying the NOTCH1-mediated WISP1 as an important player." (PMID 38269089, 2023). "Our data show that the absence of Notch1 or Notch2 tends to accelerate melanoma tumor development and growth." (PMID 36672468, 2023). "It is possible that BP mouse melanocytes that form melanoma do not express Notch1, and that the Notch1 expression seen in tumors from the Notch2 knockout group is a result of Notch2 knockout, i.e., compensating for the loss of Notch2 expression." (PMID 36672468, 2023). "The level of NOTCH1 signaling greatly affected the proliferation rate of melanoma cells in a non-linear fashion." (PMID 35163478, 2022). "In this study, we aimed to reveal the role of SPAG5 in melanoma and clarify whether FOXM1 (forkhead box protein M1) /ADAM17 (A disintegrin and metalloproteinase 17) /NOTCH1 signaling was involved." (PMID 35138218, 2022). "Moreover, the ERBB2/ERBB3 complex seems to be a promising target for combination tumor therapy in cutaneous melanoma, and activated NOTCH1 and ERBB2/ERBB3 signaling are involved in melanoma pathogenesis, supporting our data." (PMID 33786987, 2021). "Further, the protein level of Notch 1 and p-AKT in melanoma samples was detected by IHC." (PMID 32015216, 2020). "Both the tumor vasculature-normalizing and antimetastatic effects of CQ were completely blunted when melanoma cells were implanted in mice lacking Notch1 in ECs." (PMID 29371595, 2018).
melanoma (continued). "In addition, we discovered that neutralization of TGF-β1 in the co-culture system significantly reduced the inhibitory effects of Notch1 on CD8+T lymphocyte apoptosis, proliferation and activation induced by melanoma cells." (PMID 29301578, 2018). "Moreover, Notch1 and NRG1 expression in melanoma promoted cell growth by activating PI3Kinase/Akt signaling pathway and facilitating the accumulation of p27." (PMID 29301578, 2018). "Proliferative activity (Ki67 positivity) of melanoma cells was particularly weaker when adjacent to CAF, suggesting that CAF carrying high Notch1 activity in GOFNotch1 mice might release tumor suppressive factor(s)." (PMID 26562315, 2015). "It was also reported that aberrant NOTCH1 activation can induce BCL-2 overexpression and increase cell survival, and the noncanonical activation of NOTCH1 by membrane type matrix metalloproteinase sustains melanoma cell growth." (PMID 25149541, 2014). "For example, the melanoma oncogene Akt, which signals through a pathway involving PI3-kinase, requires Notch1 to transform melanocytes under hypoxic conditions and to allow tumor growth in vivo by maintaining cells in a proliferative state and protecting them from stress-induced cell death." (PMID 24281103, 2010). "In melanoma, β-catenin mediates oncogenic activity by also cross-talking with the WNT pathway or by regulating N-cadherin, with different effects on tumorigenesis depending on Notch1 activation." (PMID 19828018, 2009). "A three-day treatment with anti-N1 induced 75%, 80% and 55% cell death in the K457 (human) and the YUMM1.7 and YUMM2.1 (mouse) melanoma lines, respectively, but did not affect either human or mouse melanocytes, which express low or undetectable Notch1 levels compared to melanoma cells." (PMID 39491031, 2024). "Our previous work demonstrated that RNAi-mediated Notch1 inhibition promoted an inflamed TME by reducing immunosuppressive cytokines and factors (e.g., IL10, TGFβ, ARG1), immunosuppressive cells (MDSCs and Tregs); and by increasing IFNγ and CD8+ T cells in the melanoma TME." (PMID 39491031, 2024). "In-line with this, melanoma and NSCLC patients who did not respond to immunotherapy showed seldom NOTCH1 mutation, while a marked correlation between NOTCH1/2/3 mutation and better outcome with an immune checkpoint inhibitor (ICI) were found in EGFR/ALK WT NSCLC patients." (PMID 33968932, 2021). "Overall, our data showed that turning ‘OFF’ Notch1 signaling in MSC-DF could increase melanoma invasion and metastasis, but not skin growth." (PMID 27813493, 2016). "Additionally, as NUMB is a known NOTCH inhibitor, we analyzed the expression of NOTCH1 using TCGA melanoma patient data and found a non-significant decreasing trend in NOTCH1 expression with PLK1-low/NUMB-high expression when compared to PLK1-high/NUMB-low levels." (PMID 38184733, 2024). "In addition, Demcizumab (anti-Notch ligand, DLL4 antibody), OMP-52M51 (anti-Notch1 antibody), OMP-18R5 (anti-Wnt receptor, FZD monoclonal antibody) and BBI608 (inhibitor of Stat3 and β-catenin pathways) could be better therapeutic agents to combat melanoma." (PMID 28137308, 2017). "Western blot analyzed the expression of SOX10, Notch1, and HES1 in melanoma cell treated with or without miR-222-3p inhibitor." (PMID 35585935, 2022). "Gene mutations are often involved in tumorigenesis, the clustered deletions were found in ABL1, NOTCH1, RET, STK11, GNA11, and JAK3 genes in CRC, melanoma, and non-small cell lung cancers." (PMID 32850446, 2020). "Additionally, the present study found NOTCH1, c‐Myc, and Cyclin E to be consistently regulated by FBXW7 in melanoma as opposed to Aurora A (inconsistent) and myeloid cell leukemia sequence‐1 (MCL1) (unregulated)." (PMID 33822486, 2021). "Deletion of Notch1 in CAF may result in change of a set of soluble factors and microenvironmental cues, which preferentially or sufficiently affects melanoma invasion, but not growth property." (PMID 26562315, 2015).
ovarian carcinoma (105 papers, 2005 to 2026). A malignant neoplasm originating from the surface ovarian epithelium. "High expression of Notch1 is associated with the EMT in ovarian cancer tissue, conferring chemo-resistance on ovarian cancer cells." (PMID 36998461, 2023). "The study revealed that NOTCH1 mutation is probably a driver of lymph node metastasis in ovarian cancer, which offers new ideas for the treatment of ovarian cancer lymph node metastasis with NOTCH inhibitors." (PMID 36982170, 2023). "To further investigate the role of NOTCH1-p.C720fs mutation in ovarian cancer metastasis in vivo, we assessed the effect of NOTCH1-p.C720fs mutation on the metastatic ability of xenografts in nude mice." (PMID 36982170, 2023). "More importantly, this study revealed that NOTCH1 mutation is probably a driver event of lymph node metastasis in ovarian cancer, which offers new thoughts for the treatment of ovarian cancer lymph node metastasis with NOTCH inhibitors." (PMID 36982170, 2023). "Specifically, the activation of Jag1/Notch1 signaling has been associated with chemoresistance in many human tumors, including ovarian cancer, and the activation of the Notch1 signaling induces resistance to cisplatin." (PMID 33681228, 2021). "In the ovarian cancer, Dll4 and Notch 1 were associated with VEGFR1 and VEGFR2 expression respectively, and impacted microvessel density." (PMID 32014047, 2020). "Knockdown of MGAT3 reduced the growth of ovarian cancer in a mouse model, and the modification of Notch1 with bisecting GlcNAc was shown to cause lysosomal degradation of Notch1 and be involved in this cancer-suppressive phenotype." (PMID 31936666, 2020). "Alniaimi AN reported that increased Notch1 expression is associated with poor overall survival in patients with ovarian cancer." (PMID 32547317, 2020). "Notch1 inhibition causes cell cycle arrest at G0/G1 in ovarian cancer cells and glioma cancer cells, which is consistent with the result of cell cycle analysis upon inhibition of Furin in c-Myc-driven ovarian cancer." (PMID 29423060, 2018). "Association of activation of NOTCH1 signaling with chemoresistance and metastasis of ovarian carcinoma has been reported." (PMID 27489349, 2016). "In conclusion, Notch1-3, Jagged1 and Hes1 are more highly expressed in highly malignant ovarian cancers, and upregulation of Notch pathway component protein expression in ovarian cancer is associated with shortened overall and disease-free survival, especially in patients with advanced tumors." (PMID 40630953, 2025). "Next, we further explored whether the NOTCH1 mutation (NM_017617: exon 13: c.2104_2111del: p.C702fs) found in metastatic lymph nodes could be related to metastasis in ovarian cancer." (PMID 36982170, 2023). "Moreover, KLF9 inhibited Notch1 promoter activity in ovarian cancer cells and a loss of KLF9 expression in tumors was predictive of worse patient prognosis." (PMID 38067370, 2023). "In addition, MALAT1 decreased sensitivity of cisplatin in ovarian cancer was also reported to be associated with the Notch1 signaling pathway." (PMID 32708561, 2020). "However, Notch 1 mRNA high expression was associated with favorite OS in clinical stage III ovarian cancer patients, HR 0.83 (0.7–0.98), p = 0.03." (PMID 28415574, 2017). "SNORA72 elevates mRNA and protein expression levels of Notch1 and c-Myc in parental cells, thereby activating the stemness transformation of ovarian cancer cells." (PMID 40408479, 2025). "correlation; while in ovarian cancer tissues, the expression of Notch1 and VEGFR2 was correlated with micro vessel density, with Notch1 expression increased in ovarian tumor tissues." (PMID 40630953, 2025). "DAPT can downregulate the expression of Notch1 and Hes1 in a dose- and time-dependent manner, inducing growth inhibition and apoptosis in ovarian cancer A2780 cells." (PMID 40755759, 2025). "Of these, all but NOTCH1 are among the top 9 significantly recurrent genes identified in the TCGA ovarian carcinoma cohort." (PMID 39115191, 2024).